GDF15 (growth differentiation factor 15)
Diseases named in the same sentence as GDF15 in open-access papers (continued):
Sharing a sentence is not in itself a finding about the gene and the disease.
non-alcoholic fatty liver disease (14 papers, 2018 to 2026). "Here we find that, in addition to suppressing appetite, GDF15 counteracts compensatory reductions in energy expenditure, eliciting greater weight loss and reductions in non-alcoholic fatty liver disease (NAFLD) compared to caloric restriction alone." (PMID 37380764, 2023). "Other human studies in non-alcoholic fatty liver disease (NAFLD) have provided evidence that GDF15 levels are significantly associated with advanced fibrosis and could also be potentially involved in linking type 2 diabetes and fibrosis in NAFLD." (PMID 40565178, 2025). "quantified GDF-15 expression and secretion levels in hepatic tissue using transcriptomic and proteomic analysis and found that GDF-15 positively correlates to fibrosis progression in nonalcoholic fatty liver disease (NAFLD)." (PMID 34975851, 2021). "Moreover, GDF15 reduces lipid accumulation thus preventing diseases such as Non‐Alcoholic Fatty Liver Disease." (PMID 38650174, 2024). "Our findings are in accord with those of previous studies which suggested that serum GDF15 levels were elevated in patients with chronic liver diseases such as nonalcoholic fatty liver disease (NAFLD) and chronic hepatitis B or C virus infection and supplement those of previous studies." (PMID 33178828, 2020).
preeclampsia (14 papers, 2015 to 2026). Preeclampsia is a hypertensive disorder of pregnancy that is characterized by new-onset hypertension with proteinuria presenting after 20 weeks of gestation, and depending on mild or severe forms may initially present with severe headache, visual disturbances, and hyperreflexia. "Among the risk loci identified in the meta-analysis included in MoBa, PGR-TRPC6 was moderately associated with preeclampsia (p = 1.3×10−3) and GDF15 with preeclampsia labeled as ‘serious’ in the MBRN (p = 6.7×10−3)." (PMID 39764105, 2024). "Decreased GDF-15 levels have been correlated with preeclampsia and loss of pregnancy." (PMID 34091589, 2021). "Downregulated GDF-15 in the circulatory system of patients with preeclampsia is indicative of a potential correlation between GDF-15 and PIH." (PMID 39224743, 2024). "There is agreement on the relationship between preeclampsia or miscarriage and maternal serum GDF-15 concentration." (PMID 34291416, 2022). "One case control study (n=101) reported an outcome of gestational hypertension, finding that women with gestational hypertension had elevated levels of Growth/Differentiation Factor 15 (GDF-15) in the second and third trimesters compared to controls (reported with significance P<.05)." (PMID 41019841, 2025). "We then explored whether the results were changed if we restricted to studies that excluded preeclampsia or other diseases that may influence GDF-15 expression during their sample selection." (PMID 36742413, 2023). "What’s more, 5 GEO datasets (including GSE70493, GSE65737, GSE128381, GSE154377 and GSE203346) and 4 articles excluded preeclampsia or other diseases that may influence GDF-15 expression during sample selection." (PMID 36742413, 2023). "Furthermore, placental GDF15 mRNA concentrations were elevated in preeclampsia when compared to control samples from term placentas; this elevation was also observed in maternal and fetal circulation." (PMID 28380025, 2017). "However, no previous study had performed a functional characterization of rs888663 nor had tested the hypothesis that noncoding GDF15 SNPs affect GDF15 levels in PE or gestational hypertension (GH)." (PMID 41793551, 2026). "Likewise, the observation that GDF-15 levels are elevated to a lesser extent in women with preeclampsia (with the more profound reduction found in late-onset cases) suggests that GDF-15 is a potential biomarker for tracking pregnancy and pregnancy-related complications." (PMID 32508832, 2020). "Similarly, the expression of SDC1, NPPB (natriuretic peptide B), GDF15 (growth differentiation factor 15), and ADAMTS6 (ADAM metallopeptidase with thrombospondin type 1 motif 6) all had a lower expression in our experimental exposures, and all are lower in preeclampsia." (PMID 34150771, 2021).
steatosis (14 papers, 2017 to 2026). Increased lipid within the cytoplasm of cells. "We also observed increased fatty acid oxidation in hepatocytes and reduced macrophage recruitment as causes of GDF15-induced improvement of steatosis and inflammation." (PMID 29717162, 2018). "GDF-15 was positively associated with follow-up steatosis (β = 37.14, p = 0.006)." (PMID 41836939, 2026). "Instead, GDF15 derived from TFEB-overexpressing KCs appears to contribute to the regulation of steatosis, possibly via the ability of this cytokine to enhance macrophage FAO capacity." (PMID 41665896, 2025). "Dams showed excessive lipid accumulation in the liver and markers of liver damage in their circulation (elevated ALT and GDF15), which are indicative of steatosis and NAFLD." (PMID 38671859, 2024). "We also analyzed the expression levels of Trem2, Anxa2, Ttc39a, and Gdf15 across various stages of the disease, including steatosis, NASH, and fibrosis." (PMID 39697329, 2024). "It is reported that metformin prevents weight gain and the steatosis by elevating GDF15, a peptide hormone that responds to stressors and lowers glucose levels in the absence of GDF15 action." (PMID 36005486, 2022). "GDF15-knockout mice exhibited aggravated NAFLD phenotypes such as increased steatosis, hepatic inflammation, fibrosis, liver injury, and metabolic deterioration and expression of hepatic Gdf15 reduced lipid accumulation in liver and NAFLD progression." (PMID 33003626, 2020). "Gdf15-knockout mice exhibited aggravated NASH phenotypes such as increased steatosis, hepatic inflammation, fibrosis, liver injury, and metabolic deterioration." (PMID 29717162, 2018). "In line with this, hepatic GDF15 expression directly correlated with IL-1β expression and steatosis severity in NAFLD." (PMID 30533221, 2018). "In contrast, we noted a direct correlation between hepatic GDF15 expression and steatosis assessed by histologic means." (PMID 30533221, 2018). "Taken together, these data demonstrate that GDF15 is essential for the regulation of alcohol-mediated liver injury and steatosis." (PMID 29222479, 2017). "In line this with notion, GDF15 expression directly correlated with steatosis severity in our study, a critical feature of NAFLD which could be reverted by weight loss." (PMID 30533221, 2018). "(iv) Hepatic GDF15 expression directly correlates with features of human NAFLD i.e., IL-1β expression and steatosis." (PMID 30533221, 2018). "Moreover, the relationship between GDF-15 and different metabolic parameters such as HOMA-IR or steatosis score, connects GDF-15 to metabolic disturbances beyond adiposity." (PMID 41597417, 2026). "Circulating GDF15 levels have been found to increase in patients with MASH compared to healthy controls or patients without simple steatosis." (PMID 40076667, 2025). "In addition, the expression of hepatic GDF15 in NAFLD directly correlates with IL-1β content and the severity of steatosis." (PMID 35845807, 2022). "GDF15 is expressed in the liver, and patients with nonalcoholic steatohepatitis exhibited increased systemic GDF15 level when compared to healthy controls or patients without simple steatosis." (PMID 30533221, 2018).
thyroid cancer (14 papers, 2012 to 2025). "Specifically in thyroid cancer, quercetin induces anticancer activity by upregulating pro-NAG-1/GDF15 in differentiated thyroid cancer cells, leading to the induction of apoptosis and cell cycle arrest." (PMID 40943396, 2025). "Overall these findings suggest that GDF15 is induced by mitochondrial stress in thyroid cancer cells and functions as a mitokine through downstream STAT3 activity to promote cancer progression." (PMID 36642986, 2023). "A higher GDF-15 mRNA expression was noted in the malignant thyroid neoplasms including FTC, FVPTC, and CPTC in comparison to FTA, with a fold change between the malignant and benign groups being more than 244.18 times." (PMID 37905271, 2023). "In thyroid cancer, quercetin plays a role in upregulating Pro-NAG-1/GDF15 in differentiated thyroid cancer cells leading to apoptosis induction and cell cycle arrest." (PMID 35956766, 2022). "The knockdown of GDF15 impedes metastatic behaviors, indicating the tumor-promoting effect of GDF15 in thyroid cancer." (PMID 34948431, 2021). "Our data strongly suggested the possibility of an aberrant GDF-15 expression occurring in all malignant thyroid tumors included in the study, with the expression being strikingly higher in CPTC and FVPTC than in FTC, though statistically not of much help in differentiating among them." (PMID 37905271, 2023). "The GDF-15, belonging to the human transforming growth factor-β (TGF-β) family, has been studied in various malignancies including thyroid cancer." (PMID 37905271, 2023). "The hepatic GDF15 affected thyroid morphogenesis via a TSH-independent mechanism, affecting aggressive features of thyroid cancers." (PMID 36046792, 2022).
cervical cancer (13 papers, 2018 to 2024). A primary or metastatic malignant neoplasm involving the cervix. "This association between the ErbB2 receptor and GDF15 has also been studied in the context of cervical cancer cells, demonstrating that GDF15 also activates ErbB2 in this context and the PI3K/AKT and MAPK/ERK signaling pathways." (PMID 38892145, 2024). "In cervical cancer cells, GDF15 directly promoted cell proliferation and significantly increased cell cycle progression." (PMID 37147528, 2023). "Recent studies have demonstrated that GDF15 may also be implicated in a variety of neoplastic biological processes, including carcinogenesis and progression of non-small-cell lung carcinoma, cervical cancer, prostate cancer, hepatocellular carcinoma, colorectal cancer, and leukemia." (PMID 38082448, 2023). "In cervical cancer cell lines, including HeLa cells, GDF-15 promotes proliferation through phosphorylation of ErbB2, a member of the epithelial growth factor (EGF) receptor, and activation of PI3K/Akt and ERK signaling pathways." (PMID 36008442, 2022). "In the present research, we further investigated the influences of GDF15 on the migration of cervical cancer cells." (PMID 33098235, 2020). "Subsequently, GDF15 expression was detected in cervical cancer cell lines (HeLa, C‐33a, SiHa, CaSki and HT‐3) and human cervical epithelial cell line End1/E6E7." (PMID 33098235, 2020). "First, we explored the expression of GDF15 in different cervical cancer tissues by immunohistochemistry assay." (PMID 33098235, 2020). "Next, we explored the possible molecular mechanisms of how GDF15 inhibited the migration of cervical cancer cells." (PMID 33098235, 2020). "The mRNA and protein expressions of GDF15 were stronger in cervical cancer cell lines compared with the human cervical epithelial cell line (P < 0.05)." (PMID 33098235, 2020). "In this section, we investigated the effect of GDF15 on EMT‐related gene expressions in cervical cancer cells." (PMID 33098235, 2020). "GDF15 has been previously reported as a biomarker of cervical cancer, but its biological functions need to be further studied." (PMID 33098235, 2020). "A previous study pointed out that GDF15 expression was elevated in cervical cancer, and it had been suggested as a novel potential biomarker." (PMID 33098235, 2020). "Our finding illustrated that GDF15 regulated the TGF‐β/Smad2/3 signaling pathway in cervical cancer cells." (PMID 33098235, 2020). "Knockdown of GDF15 markedly affects epithelial–mesenchymal transformation‐related gene expression and suppresses the migration and invasion abilities of cervical cancer cells through the transforming growth factor‐β/Smad2/3/Snail1 pathway." (PMID 33098235, 2020). "In this study, we explored the regulatory role of GDF15 on the TGF‐β/Smads signaling pathway in cervical cancer cells." (PMID 33098235, 2020). "In this study, we explored the role of GDF15 on the migration of cervical cancer cells and its mechanism." (PMID 33098235, 2020). "In this study, we verified that the expression of GDF15 at both mRNA and protein levels was significantly increased in cervical cancer tissues and cell lines." (PMID 33098235, 2020). "In summary, we report here that GDF15 knockdown inhibits migration and invasion of cervical cancer cells in vitro through the TGF‐β/Smad2/3/Snail1 pathway." (PMID 33098235, 2020). "Overall, these data strongly supported that GDF15 knockdown suppressed migration and invasion of cervical cancer cells through the TGF‐β/Smad2/3 signaling pathway." (PMID 33098235, 2020). "In conclusion, our study showed that silencing of GDF15 significantly inhibits the progression of cervical cancer through the TGF‐β/Smad2/3/Snail1 pathway." (PMID 33098235, 2020). "The addition of TGF‐β1 partially abolished the inhibitory effects of GDF15 knockdown on the migration and invasion of cervical cancer cells." (PMID 33098235, 2020).
cervical cancer (continued). "Here, we report that GDF15 expression is enhanced in cervical cancer tissues, as well as in cultured cervical cancer cells." (PMID 33098235, 2020). "All of these data suggested that GDF15 promoted tumor formation of cervical cancer cells, potentially via enhanced cell proliferation in vivo." (PMID 29636108, 2018). "GDF15 expression in human cervical cancer cell lines was detected using immunocytochemistry (a) and western blotting (b)." (PMID 29636108, 2018). "Our data demonstrated that GDF15 promoted the proliferation of cervical cancer cells via the up-regulation of CyclinD1 and CyclinE1 and the down-regulation of p21 through both the PI3K/AKT and MAPK/ERK signaling pathways in a complex with ErbB2." (PMID 29636108, 2018). "The expression of p-ErbB2, p-AKT1, p-Erk1/2, CyclinD1 and CyclinE1 was up-regulated and the expression of p21 was down-regulated in GDF15-overexpressing and rhGDF15-treated cervical cancer cells." (PMID 29636108, 2018). "GDF15 expression was also found to be elevated in cervical cancer compared to adjacent normal tissue in a microarray-based study." (PMID 29636108, 2018). "All of these results demonstrated that the GDF15 protein stimulated the proliferation of cervical cancer cells in vitro in both an autocrine and a paracrine manner." (PMID 29636108, 2018). "Immunohistochemistry was used to detect GDF15 expression in normal cervix and in different cervical cancer lesions." (PMID 29636108, 2018). "All of these data suggested that GDF15 promoted cervical cancer cell proliferation and tumor formation via activation of the PI3K/AKT and MAPK/ERK signaling pathways." (PMID 29636108, 2018). "Together, these results showed that GDF15 accelerated the cell cycle in cervical cancer cells at the transition from G0/G1 to S phase and suggested that GDF15 promoted cervical cancer cell proliferation through alterations in the cell cycle phases." (PMID 29636108, 2018). "Cell growth curves, MTT, tumor formation assays and flow cytometry were utilized to observe the effects of ectopic GDF15 expression on the proliferation and cell cycle of cervical cancer cells." (PMID 29636108, 2018). "GDF15 promoted cervical cancer cell proliferation via exogenous rhGDF15 treatment or the use of gene editing technology in vitro and in vivo and significantly accelerated the cell cycle transition from G0/G1 to S phase." (PMID 29636108, 2018). "The relative expression levels of GDF15 in these cervical carcinoma tissues were higher than that in the normal cervix (P < 0.05)." (PMID 29636108, 2018). "To investigate whether GDF15 controls the migration of cervical cancer cells through regulation of EMT‐related gene expression, we detected the invasion and migration of cervical cancer cells." (PMID 33098235, 2020). "To further investigate whether GDF15 affected cervical cancer metastasis through mediating the TGF‐β/Smad2/3 signaling pathway, we treated HT‐3 and HeLa cells with Smad2/3 activator TGF‐β1 (10 ng·mL−1) after shGDF15 transfection." (PMID 33098235, 2020). "Based on the earlier data, we concluded that GDF15 silencing could suppress the migration of cervical cancer cells via regulating the TGF‐β/Smad2/3/Snail1 pathway." (PMID 33098235, 2020). "Moreover, the result of ELISA confirmed that the level of mature GDF15 was elevated in the culture solution of cervical cancer cell lines (P < 0.01)." (PMID 33098235, 2020). "Hence these results proved that GDF15 expression was augmented in cervical cancer tissues and cell lines." (PMID 33098235, 2020). "A previous study suggested that GDF15 was a novel biomarker for the prognosis of cervical cancer." (PMID 33098235, 2020). "Taken together, we found that GDF15 silencing could regulate the EMT‐related gene expressions in cervical cancer cells." (PMID 33098235, 2020). "In the present study, GDF15 was found to be up-regulated between normal cervix and cervical cancer lesions, which suggests that GDF15 might play a role in cervical carcinogenesis." (PMID 29636108, 2018).
cervical cancer (continued). "GDF15 was identified as a novel potential biomarker of cervical cancer in a previous study." (PMID 29636108, 2018). "Cell cycle analysis showed that GDF15 overexpression accelerated the transition of cervical cancer cells from G0/G1 phase to S phase, whereas GDF15 down-regulation hindered the transition of cervical cancer cells from G0/G1 phase to S phase." (PMID 29636108, 2018). "In addition, our current study showed the down-regulated expression of FOXO1 and the up-regulated expression of C-myc in GDF15-overexpressing cervical cancer cells." (PMID 29636108, 2018). "In addition, the expression of GDF15 in 8 samples of normal cervix and 10 samples of cervical carcinoma was detected by western blotting." (PMID 29636108, 2018). "Furthermore, we explored whether GDF15 modulated cervical cancer cell migration through mediating the TGF‐β/Smad2/3 signaling pathway." (PMID 33098235, 2020). "Furthermore, GDF15 bound to ErbB2 in a protein complex in cervical cancer cells." (PMID 29636108, 2018). "GDF15 is a member of the TGF-β superfamily and has been previously identified as a new potential biomarker for cervical cancer." (PMID 36698183, 2023). "Therefore, GDF15 knockdown could impede the migration and invasion of cervical cancer cells." (PMID 33098235, 2020). "More importantly, TGF‐β1 partially reduced the regulatory effect of GDF15 silencing on EMT‐related genes expressions and the migration of cervical cancer cells." (PMID 33098235, 2020). "Growth differentiation factor 15 (GDF15), a member of the transforming growth factor β (TGF‐β) superfamily, is a prognostic biomarker of cervical cancer." (PMID 33098235, 2020). "The expression of growth differentiation factor 15 (GDF15) is increased in cervical cancer tissues, especially in metastatic cervical cancer tissue, as well as cultivated cells." (PMID 33098235, 2020). "Together, these results suggested that GDF15 activated the PI3K/AKT and MAPK/ERK signaling pathways through ErbB2 in cervical cancer cells." (PMID 29636108, 2018). "According to previous studies, GDF15 might activate PI3K/Akt signaling pathways and finally promote cell proliferation in human cervical cancer." (PMID 35721026, 2022). "Although GDF15 expression has been discovered in various carcinomas, its role in cervical cancer is not well defined." (PMID 29636108, 2018). "However, the regulatory role of GDF15 on cervical cancer cell migration and the possible mechanisms have not been clarified." (PMID 33098235, 2020). "However, the mechanism by which GDF15 promotes cervical cancer cell migration is not completely understood." (PMID 33098235, 2020). "However, the function of GDF15 in cervical cancer has not yet been reported." (PMID 29636108, 2018).